IL33 (interleukin 33)
Diseases named in the same sentence as IL33 in open-access papers (continued):
Sharing a sentence is not in itself a finding about the gene and the disease.
COVID-19 (continued). "We explored the potential associations between genetic polymorphisms in IL-33 and TSLP and COVID-19 outcomes." (PMID 37761861, 2023). "RNA sequencing of bronchoalveolar lavage fluid from COVID-19 patients also revealed significantly increased IL33 expression." (PMID 37631998, 2023). "IL-8 has been suggested as a target for anti-cancer drugs and has been associated with adverse outcomes in COVID-19 patients, along with TNF-α, IL-6, IL-1β, and IL-33." (PMID 37627815, 2023). "Tozorakimab is a high-affinity human IgG1 monoclonal antibody that neutralises IL-33 and has therapeutic potential to improve clinical outcomes in patients hospitalised with COVID-19." (PMID 37868151, 2023). "IL-22 and IL-33 showed up-regulated concentrations in the serum of patients with mild/moderate COVID-19." (PMID 36875710, 2023). "COVID-19 induces IL-33 expression in the lungs, and activated IL-33 leads to the production of sST2 type II pneumocytes." (PMID 36673069, 2023). "IL-33, TSLP, and IL-25 have been implicated as potential predictors of severe COVID-19 outcomes, associated with severe lung inflammation, making them promising candidates for disease severity control." (PMID 37761861, 2023). "Confirming this, the role of activated MCs and of IL-33 in COVID-19 pathogenesis has been shown recently, demonstrating that released alarmins and MCs are indeed important for hyperinflammatory reactions in peripheral tissues." (PMID 38067124, 2023). "Investigations have revealed that plasma IL-33 is elevated in COVID-19 patients and that it is predictive of disease severity." (PMID 37631998, 2023). "The COVID-19 group presented higher tissue immunoexpression of IL-33 compared to the CONTROL group (p = 0.013); however, it was not statistically significant when compared to the H1N1 group." (PMID 35163636, 2022). "A recent publication reported that published scRNseq data from bronchoalveolar lavage fluid from patients with mild to severe COVID-19 contained a population of cells that produce IL-33 and correlate with severity of disease." (PMID 35563282, 2022). "These events favour the progression of COVID-19, with the possible extensive injury of alveolar epithelial cells, with the release of IL-33." (PMID 36498859, 2022). "These cytokines play an essential role in inflammation, since previous studies have shown that patients recovered from COVID-19 have persistent circulating cells that produce IL-33 in response to virus-specific T-cell activation." (PMID 36362922, 2022). "IL-33, as a major member of the cytokine storm, plays a key role in the pathological changes after COVID-19." (PMID 36362440, 2022). "Although the increase in IL-33 levels is considered a predictor of severe COVID-19, its precise role at different stages of the disease is still unclear." (PMID 35327516, 2022). "A similarly large infiltration of neutrophils is observed in the lungs of COVID-19 patients, suggesting that IL-33 also induces NET formation in the lungs in response to SARS-CoV-2 infection." (PMID 36362440, 2022). "Specifically, researchers proposed a comparative morphological characterization of the respiratory nasal mucosa in chronic rhinosinusitis with nasal polyps (CRSwNP) versus COVID-19 and tissue IL-33 levels." (PMID 35327516, 2022). "Recently, an in vitro experiment confirmed the role of the cytokine storm in the generation of thrombosis in COVID-19 patients, and IL-33 plays an essential role in the cytokine storm, especially regarding the triggering of pro-thrombotic phenomena." (PMID 36498859, 2022). "In stage I of COVID-19, strong positive correlation was detected between Gal-1 and IL-33 (p = 0.00)." (PMID 35075140, 2022). "The aim of this review is to explore the potential value of the IL-33/immune cell pathway as a new target for early diagnosis, monitoring of severe cases, and clinical treatment of COVID-19." (PMID 36362440, 2022).
COVID-19 (continued). "Further studies on IL-33 are needed to develop specific immunological treatment, with the aim of blocking the cytokine storm that is responsible for the most severe form of COVID-19, in particular in patients with comorbidities." (PMID 36498859, 2022). "Systemic values of IL-1β (p = 0.001), IL-6 (p = 0.001), IL-10 (p = 0.026), IL-23 (p = 0.001), IL-33 (p = 0.001), and Gal-1 (p = 0.001) were significantly higher in COVID-19 patients in stage III compared to patients in stage I and II." (PMID 35075140, 2022). "The increased systemic values of TNF-α, IL-1β, IL-6, IL-12, IL-23, and IL-33 support the prevalence of innate pro-inflammatory mediators in the serum of subjects with a severe form of COVID-19." (PMID 34917631, 2021). "The analysis of the published scRNAseq data of bronchoalveolar lavage fluid (BALF) from patients with mild to severe COVID-19 revealed a population of IL-33-producing cells that increases with the disease." (PMID 34917631, 2021). "Moreover, apart from a variety of proinflammatory cytokines (which could possibly play a detrimental role in COVID-19), anti-inflammatory responses including IL-10 and IL-33, which have been implicated in COVID-19 disease severity, were also decreased in vaccinated individuals." (PMID 34348897, 2021). "Significantly higher concentration of TNF-α (p = 0.001), IL-1β (p = 0.001), IL-6 (p = 0.001), IL-12 (p = 0.001), IL-23 (p = 0.043), and IL-33 (p = 0.001) have been found in the sera of COVID-19 patients with severe disease." (PMID 34917631, 2021). "Interleukin (IL)-18 and IL-33 were elevated at admission in COVID-19 patients in comparison with controls." (PMID 34960684, 2021). "Age distribution, microscopic findings, and tissue IL-33 concentration of the nasal mucosa in CRSwNP versus COVID-19." (PMID 34575221, 2021). "As a previous study showed that the virus can trigger the secretion of IL-33 through activation of SARS CoV-2-derived papain-like protease (PLpro), IL-33 is considered as a predictor of severe forms of COVID-19." (PMID 34917631, 2021). "PIMS-TS children had significantly elevated levels of cytokines, IFNγ, IL-2, TNFα, IL-1α, IFNα, IFNβ, IL-6, IL-17A, GM-CSF, IL-10, IL-33 and IL-Ra in comparison to COVID-19, seropositive and control children." (PMID 33813138, 2021). "The revelation of the positive correlation between the systemic IL-33, IL-6, and IL-12 levels in serum of COVID-19 patients suggested the synergistic effect of these cytokines in the pathogenesis of COVID-19 disease." (PMID 34917631, 2021). "Together these findings show that IL-33 production is linked to SARS-CoV-2 infection and warrant further investigation of IL-33 in COVID-19 pathogenesis and immunity." (PMID 33837219, 2021). "Analysis of published scRNAseq data of bronchoalveolar lavage fluid (BALF) from patients with mild to severe COVID-19 reveals a population of IL-33-producing cells that increases with the disease." (PMID 33837219, 2021). "The ROC curve analysis of IL33 to differentiate mild from severe COVID-19 reviled that the optimum cut-off point for IL-33 was 332.08 pg/ml (AUC.634; Sensitivity 63.8%; Specificity 49.2%; 95% CI.562–0.705; p = 0.001)." (PMID 34917631, 2021). "In CRSwNP samples, IL-33 had a mean tissue concentration of 210.0 pg/7 μg total protein (±8.327, n = 25) and in COVID-19 samples 52.77 pg/7 μg total protein (± 6.869, n = 12)." (PMID 34575221, 2021). "Further, in patients with milder stage of COVID-19, positive correlation was detected between IL-33 and IL-1β (p = 0.024), IL-12 (p = 0.000), and IL-23 (p = 0.000), respectively." (PMID 34917631, 2021). "The almost unchanged ratio between IL-33 and innate immunity mediators of interest during COVID-19 progression indicates the stable dynamics of cytokine growth." (PMID 34917631, 2021). "The mean tissue IL-33 concentration in CRSwNP samples was statistically significantly higher than in COVID-19 samples (unpaired t test with Welch’s correction p < 0.0001)." (PMID 34575221, 2021).
COVID-19 (continued). "In order to determine the relationship between IL-33 and proinflammatory mediators in all stages of COVID-19, we analyzed the ratio of the systemic values of IL-33 with the values of TNF-α, IL-1β, IL-6, IL-12, and IL-23." (PMID 34917631, 2021). "The linear multiple regression model was calculated to predict the levels of IL-33 based on COVID-19 severity, IL-6, IL-1β, IL-12, TNF-α, and IL-23." (PMID 34917631, 2021). "We show that after recovery from COVID-19, individuals have persisting, circulating PBMCs that produce IL-33 in response to virus-specific T cell activation, which correlates with seropositivity." (PMID 33837219, 2021). "The tissue IL-33 concentration in CRSwNP (210.0 pg/7 μg total protein) was higher than in COVID-19 (52.77 pg/7 μg total protein) (p < 0.0001), also suggesting a different inflammatory pattern." (PMID 34575221, 2021). "We found a significantly higher serum concentration (p < 0.05) of TNF-α, IL-1β, IL-6, IL-12, IL-23, and IL-33 in patients with COVID-19 with severe disease." (PMID 34917631, 2021). "In bronchoalveolar lavage fluid from patients with mild to severe COVID-19, a population of IL-33-producing cells, which increases with the disease, was identified." (PMID 34575221, 2021). "Together these findings suggest that IL-33 has an important role in COVID-19 pathogenesis and immune response." (PMID 32962703, 2020). "The aim of this study was to investigate serum IgE, IgG, and the counts of eosinophils and basophils, as well as the levels of interleukin-10 (IL-10) and interleukin-33 (IL-33), in COVID-19 patients using fresh and frozen serum samples collected during the pandemic." (PMID 41157211, 2025). "Of the tested inflammatory cytokines/chemokines, only a few significant associations were found with COVID-19 severity: lower levels of IL-1β, IL-33 together with significantly higher levels of IL-18 were found in women with moderate/severe COVID-19 as compared to asymptomatic/mild cases." (PMID 40303405, 2025). "Likewise, severe COVID-19 patients exhibited markedly increased IL33 expression, whereas its expression was negligible in controls and mild cases." (PMID 41459501, 2025). "It has been reported that serum IL-33 levels are elevated in COVID-19 patients." (PMID 38904891, 2025). "However, in pathological conditions such as severe COVID-19, elevated sST2 acts as a decoy receptor, neutralizing IL-33 and disrupting its protective functions, thereby promoting myocardial damage, fibrosis, and ventricular dysfunction." (PMID 40710798, 2025). "Interestingly, several cytokines such as IFN-γ, IFN-α, IL-1β, IL-2, IL-12p70, IL-17A and IL-33) decreased in moderate and severe COVID-19 patients compared to mild cases or healthy controls." (PMID 38855114, 2024). "Tozorakimab was well tolerated, and post hoc analyses suggest that treatment effects may be enhanced in patients with severe COVID-19 and those with high baseline levels of serum IL-33/sST2." (PMID 37868151, 2023). "Multinomial logistic regression analysis demonstrated that individuals with high production (> control median) of IL-22 (odds ratio = 17.80 [95% CI: 6.48–48.90]; p = 0.001) and IL-33 (odds ratio = 19.0 [95% CI: 7.4–48.6]; p = 0.001) were more likely to develop COVID-19." (PMID 36875710, 2023). "However, in regard to the relation between COVID-19 and ILC2s, COVID-19 patients have higher levels of serum IL-33 than healthy subjects, along with an increased number of circulating ILC2s." (PMID 37371472, 2023). "Therefore, further research is needed to investigate the potential therapeutic targets for COVID-19 using IL-31/IL-33 axis modulation." (PMID 37240091, 2023). "IL-22 and IL-33 showed up-regulated serum concentrations in patients with mild/moderate COVID-19." (PMID 36875710, 2023). "IL-33 is released mainly by injured epithelial alveolar cells and can be upregulated in COVID-19." (PMID 36673069, 2023).
COVID-19 (continued). "IL-33 represents an attractive therapeutic target for COVID-19 because increased IL-33 levels might facilitate excess lung inflammation in patients hospitalised with COVID-19 and serum IL-33 levels correlate with poor clinical outcomes." (PMID 37868151, 2023). "IL-33 has been investigated as a marker in the pathogenesis and prediction of severe COVID-19." (PMID 37631998, 2023). "IL-33 is an alarmin produced by the epithelium during injury in diseases such as COVID-19." (PMID 37679779, 2023). "IL-22 and IL-33 are among the least explored pro-inflammatory cytokines in COVID-19." (PMID 36875710, 2023). "Herein, the refractory respiratory failure in patients with COVID-19 was associated with increased CRP, D-dimers, LDH, Ferritin, HMGB1, and IL-33, as well as higher numbers of circulating neutrophils, higher plasma levels of IL-6 and IL-10, and diminished numbers of lymphocytes and platelets." (PMID 37604833, 2023). "However, further studies of the interplay of IL-33 and sST2 and the mechanism of tozorakimab in patients with COVID-19 are required." (PMID 37868151, 2023). "In severe COVID-19, the overproduction of IL-33 may accelerate the polarization and activation of ILC2." (PMID 37631998, 2023). "In particular, PC1 reflected the known hyper-inflammatory phenotype of COVID-19 (with greatest contributions from IL-2, IL-6, IP-10, TNF-α, IL-10, IL-33 and IL-1β) which was independently associated with severe disease, requirement for invasive mechanical ventilation and mortality." (PMID 37063871, 2023). "In addition, transcriptomic analysis of bronchoalveolar lavage fluid (BALF) from COVID-19 patients showed an increased population of IL-33-producing cells with the disease severity and strong upregulation of IL-33 compared to healthy samples." (PMID 35464491, 2022). "Moreover, researchers noticed that after recovery from COVID-19, individuals still had persisting, circulating PBMCs that produced IL-33 in response to virus-specific T-cell activation, which correlated with seropositivity." (PMID 35327516, 2022). "Analyses of patients in stage II of COVID-19 revealed a moderate positive correlation between Gal-1 and IL-1β (p = 0.004) and strong positive correlations between Gal-1 and IL-23 (p = 0.001) and IL-33 (p = 0.001)." (PMID 35075140, 2022). "When analysis was performed using the O’Brien method and the functional groupings described in the Methods, we found that groups related to TH2 regulations (IL-4, IL-13, IL-33), cell metabolism (lep, lep-R) and interferons (IFNα, IFNβ, IFNγ) were also predictive of life-threatening COVID-19." (PMID 35386702, 2022). "An increased immunoexpression of the tissue biomarkers CASP-1, IL-33, ACE2, B1R and B2R was observed in the alveolar septum of the COVID-19 patients, associated with a higher density of IgE+ MCs, tryptase+ MCs and TB-stained MCs, in addition to the presence of intra-alveolar edema." (PMID 35163636, 2022). "IL-33 released by airway epithelial cells functions as an important checkpoint cytokine, which plays an important role in immune cell regulation and cytokine regulation in COVID-19." (PMID 36362440, 2022). "In conclusion, we speculate that IL-33 is likely to exacerbate tissue and organ damage by enhancing neutrophil migration, infiltration, and aggregation in the development of COVID-19 pathology." (PMID 36362440, 2022). "COVID-19 is associated with cytokine storm with exaggerated inflammatory response characterized by release of large amounts of cytokines like IL-1b, IFN-α, IFN-γ, TGF-α, IL-6, IL-12, IL-18, and IL-33." (PMID 35382491, 2022). "The second speculation is further consolidated by a recent report, in which expression of interleukin-33 levels is correlated with seropositivity in COVID-19 convalescent individuals." (PMID 36359409, 2022).
COVID-19 (continued). "In the literature, it has been reported that serum IL-33 levels are up-regulated in elderly patients affected by COVID-19, an expression of the epithelial damage induced by the interaction between the airway epithelium and activated immune cells, linking them to severe outcomes." (PMID 36498859, 2022). "In addition, we found that cytokines related to TH2 regulations (IL-4, IL-13, IL-33), cell metabolism (lep, lep-R) and interferons (IFNα, IFNβ, IFNγ) were also predictive of life-threatening COVID-19." (PMID 35386702, 2022). "Here, we provide a comprehensive overview of the biological characteristics of IL-33 and its roles in the physiology and pathology of COVID-19, as well as the potential mechanisms, with the aim of exploring the value of IL-33 as a new target for the prevention and treatment of COVID-19." (PMID 36362440, 2022). "However, the mechanism by which IL-33 regulates the pathological development of COVID-19 and its potential ability to target cells of the innate and adaptive immune systems have not yet been extensively explored." (PMID 36362440, 2022). "Overall, we speculate that IL-33 functions in the development of COVID-19 pathology by exacerbating tissue and organ damage by enhancing the proliferation, migration, and activation of macrophages." (PMID 36362440, 2022). "Indeed, patients with COVID-19 had very low IL-33 expression, which was significantly reduced compared to that of control subjects." (PMID 36498859, 2022). "In conclusion, inflammatory cytokine storm factors represented by IL-33 are of great significance in the monitoring and prognosis of COVID-19 to improve the early detection of patients who are severely affected by the infection and guidance for clinical treatment." (PMID 36362440, 2022). "IL-33 correlates with clinical parameters of COVID-19 and might represent a promising marker as well as a therapeutic target in COVID-19." (PMID 34917631, 2021). "Furthermore, the different tissue concentrations of IL-33 in the nasal mucosa of CRSwNP and COVID-19 patients were assessed." (PMID 34575221, 2021). "The members of IL-1 family including IL-1β and IL-33 may contribute to the inflammation and antiviral immune regulation in COVID-19." (PMID 34054828, 2021). "Indeed, IL-33 has been purposed as a key player in the pathogenesis of COVID-19, possibly being involved in early activation of innate immune responses, but also in later stages of the disease by inducing lung fibrosis." (PMID 34950134, 2021). "Finally, analysis of the cytokine profile in COVID-19 patients revealed unique correlation of an IL-12p70/IL33 and IgG seroconversion, which correlated with disease severity." (PMID 33568715, 2021). "Our findings also lend support to the hypothesis of an IL-33/ST2 axis led pathophysiology in COVID-19." (PMID 34441830, 2021). "By contrast, in individuals with more severe forms of COVID-19 (e.g., presenting pneumonia) IL-33 may paradoxically upregulate ST2 (its own receptor on Treg cells), with an inhibitory effect on the suppressive functions of these lymphocytes." (PMID 33530550, 2021). "The role of IL-33 in COVID-19 is unknown, but it is speculated that IL-33 might even play a key role in driving all stages of this disease, including the progression to healing or hyperinflammation and thromboses." (PMID 34575221, 2021). "Moreover, analysis revealed a positive correlation between the serum values of IL-33 and IL-12 (p = 0.001), IL-33 and IL-6 (p = 0.001), and IL-6 and IL-12 (p = 0.001) in patients with COVID-19." (PMID 34917631, 2021). "The IL-33/ST2 axis is likely playing a role in COVID-19 systemic manifestations." (PMID 34441830, 2021). "IL-33 has, for example, emerged as a molecular biomarker for severe COVID-19 by BAL analysis." (PMID 34867933, 2021). "However, in COVID-19 patients, it was negatively correlated with IL-1α and IL-33." (PMID 38855114, 2024).